MAP3K7CL (MAP3K7 C-terminal like)
Synonyms: C21orf7; TAK1L; TAKL; TAKL-1; TAKL-2; TAKL-4; HC21ORF7
Tractability: No criterion of Open Targets' tractability assessment is met for any kind of drug.
Gene: Protein-coding gene on chromosome 21 (29,077,060 to 29,175,889, forward strand). Ensembl gene ENSG00000156265.
Subcellular location (Human Protein Atlas): Nucleoplasm
Gene Ontology:
Molecular function: protein binding
Cellular component: cytosol; nucleus
Genetic constraint (gnomAD): Loss-of-function variants: 10 observed, 13.05 expected, observed/expected ratio (o/e) 0.77, 90% interval 0.47 to 1.3. The upper end of that interval is the gene's LOEUF score, 1.3, which puts it in group 5 of 6, group 1 being the genes least tolerant of losing a copy. Missense variants: 148 observed, 167.92 expected, observed/expected ratio (o/e) 0.88, 90% interval 0.77 to 1.01. Synonymous variants: 63 observed, 64.64 expected, observed/expected ratio (o/e) 0.97, 90% interval 0.8 to 1.2.
Homologues: Orthologues: macaque MAP3K7CL (98% identical), guinea pig MAP3K7CL (94% identical), rabbit MAP3K7CL (94% identical), dog MAP3K7CL (90% identical), chimpanzee MAP3K7CL (85% identical), rat Map3k7cl (75% identical), pig MAP3K7CL (58% identical). Paralogues in human: MAP3K7 (45% identical), PKDCC (15% identical).
Diseases named in the same sentence as MAP3K7CL in open-access papers:
MAP3K7CL is named in the same sentence as 9 diseases in open-access papers, as found by Europe PMC text mining. Sharing a sentence is not in itself a finding about the gene and the disease. The quoted sentences say what the papers report.
non-small cell lung carcinoma (2 papers, 2021 to 2024). A group of at least three distinct histological types of lung cancer, including non-small cell squamous cell carcinoma, adenocarcinoma, and large cell carcinoma. "In a gene expression study on tumor-educated leukocytes mRNA isolated from non-small cell lung cancer patients, MAP3K7CL was found to be downregulated." (PMID 38886662, 2024).
coronary artery disease (1 paper, 2019). "The corresponding gene MAP3K7CL is overexpressed in arteries, including coronary arteries and the aorta, and associated with coronary artery disease, and a recent genome-wide association study (GWAS) for heart failure suggests it is the top risk gene for coronary artery disease." (PMID 31552105, 2019).
MAP3K7CL also shares sentences with these, for which no sentence is quoted: tumor (2 papers); bladder cancer (1); cancer (1); dengue (1); heart failure (1); influenza (1); lymphoma (1).